MIR3618 (microRNA 3618)
Synonyms: hsa-mir-3618
Gene: MicroRNA gene on chromosome 22 (20,085,746 to 20,085,833, forward strand). Ensembl gene ENSG00000284140.
Homologues: Orthologues: chimpanzee MIR3618 (100% identical), dog MIR3618 (100% identical), guinea pig MIR3618 (100% identical), macaque MIR3618 (100% identical), mouse Mir3618 (100% identical), pig MIR3618 (100% identical), rabbit MIR3618 (100% identical), rat Gm24572 (100% identical).